EPHA2 (EPH receptor A2)
Diseases named in the same sentence as EPHA2 in open-access papers (continued):
Sharing a sentence is not in itself a finding about the gene and the disease.
tumor (continued). "By targeting EphA2 on endothelial cells, [225Ac]AJ210 could disrupt tumor vasculature, impairing blood supply to the tumor." (PMID 40225586, 2025). "An oncolytic vaccinia virus armed with an Epha2-directed BiTE and the oncolytic adenovirus ICOVIR-15K expressing an EGFR-targeting BiTE, respectively, showed robust T-cell activation and bystander cell-mediated cytotoxicity in vitro and in murine tumor models." (PMID 39789356, 2025). "Given the importance of axon-guided migration in GBM, we included inhibitors of Ephrin receptors (ALW-II-41–27 for EphA2, NVP-BHG712 for EphB4, and Ehp-inhibitor-1), and the CXCL12/CXCR4 axis (motixafortide), known to regulate directed migration in the hypoxic tumour core in immunotherapy." (PMID 41390851, 2025). "On-target, off-tumor toxicities of ADCs can become dose-limiting in the clinic when choosing targets with low-to-moderate expression levels on normal tissues, such as TROP2, Epithelial cell adhesion molecule (EpCAM), and EPH receptor A2 (EphA2)." (PMID 40005994, 2025). "EphA2 inhibitors can significantly inhibit PT-positive tumor growth, indicating that PT plays an important role in the development of PT-positive ESCC, and suppression of EphA2 could be a potent therapeutic strategy for patients with PT-positive ESCC." (PMID 40615663, 2025). "Specific proteins on exosomes, such as epidermal growth factor receptor (EGFR), Ephrin type-A receptor 2 (EphA2) and Epithelial cell adhesion molecule (EpCAM), are increasingly used to distinguish between tumor-derived exosomes and non-tumor-derived exosomes." (PMID 40612948, 2025). "We then tried to overexpress EphA2 using a retroviral vector and discovered that this unfortunately did not recapitulate results we observed in tumor burden with the lentiviral vector." (PMID 40867322, 2025). "For instance, some NPs and TCMs exert anti-VM effects by regulating the expression of key VM-related molecules such as VE-cadherin, EphA2, and HIF-1α; inhibiting signaling pathways including PI3K/Akt and Wnt/β-catenin; suppressing EMT; and destroying the stemness characteristics of tumor cells." (PMID 41019994, 2025). "Knockdown of EphA2 dampened the CSC phenotype and the tumour-initiating frequency of OSCC cells." (PMID 38916835, 2024). "Imaging of the EphA2-negative MCF-7 xenograft showed no uptake of 68Ga-labeled BCY18469 in the tumor proving the compounds' specificity." (PMID 39239524, 2024). "Non-canonical EphA2 signaling has formerly only been studied in the context of tumor metastasis, carcinogenesis, and EMT." (PMID 39466050, 2024). "Evidently, the chances of tumor immune escaping are high due to an increase in EphA2-negative cells for no reason." (PMID 38655095, 2024). "- EphA2-TEA-VV infected tumor cells induced T cell activation.- EphA2-TEA-VV redirects T lymphocytes to EphA2-positive cancer cells.- EphA2-TEA-VV induces bystander killing of non-infected tumor cells and enhanced antitumor activity in vivo." (PMID 38464532, 2024). "Additionally, EphA2 can be activated through phosphorylation events mediated by AKT/RSK/PKA, thereby promoting tumor progression." (PMID 39506843, 2024). "Also, BDNF, GDNF, NGF, and axon guidance molecules, such as CX3CL1, EphA2, CCL2, Slit, and so forth, are groups of neuroactive chemicals generated by the nerves involved in tumor–nerve interaction." (PMID 39346791, 2024). "In summary, while EphA2 promotes cancer progression in ESCC, EphA7, EphA3, and EphA5 act as tumor suppressors, suggesting that members of the Eph family may have opposing effects depending on the tumor context." (PMID 39839790, 2024).
tumor (continued). "Regardless of the presence of PD-1 antibody, tumor growth in mice treated with EphA2-a-CAR-T cells was significantly inhibited." (PMID 38339374, 2024). "EphA2, a member of the tyrosine kinase family enriched in the PI3K/AKT pathway 27, has been shown to play a pivotal role in maintaining tumor cell stemness or promoting tumor growth through unconventional pathways 24-26, 28-31." (PMID 39346536, 2024). "The results showed that EphA2 expression was significantly elevated in OSCC tissue compared with that in oral normal tissue but was not correlated with tumour size, lymph node metastasis, distant metastasis, or tumour stage." (PMID 38916835, 2024). "Accordingly, RNF5 depletion using shRNA approaches or inhibition using the INH2 compound increased cell surface EphA2 levels, decreased ERK and AKT phosphorylation, and altered the balance of EphA2 phosphorylation at S897 and Y772, resulting in a tumor-suppressor function." (PMID 39596256, 2024). "Recently published data demonstrated that endogenous lactate dehydrogenase A (LDHA) was upregulated in renal carcinoma cells and promoted EphA2 overexpression in cancer-derived exosomes, which promoted M2 macrophage polarization through the activation of the PI3K/AKT/mTOR and tumor progression." (PMID 39596256, 2024). "Recent data from our group and others indicate that tumor cell–intrinsic factors in PDAC, such as CXCL1, EPHA2, USP22, EGFR, and the prostaglandin synthesis enzyme COX-2, promote myeloid cell infiltration that negatively impacts T cell infiltration, function, and tumor rejection." (PMID 39298269, 2024). "The measurement of serum EphA2 in patients with CRC is expected to be a practical, minimally invasive screening test for early detection and potentially more effective than conventional tumor markers." (PMID 39766211, 2024). "Even though these results are still very preliminary and the functional impact of PROTAC2-mediated degradation of EphA2 in tumor cells is still unexplored, PROTAC may represent a concrete opportunity for targeting EphA2." (PMID 39596256, 2024). "Our previous studies demonstrated excellent delivery of EphA2 siRNA through 1,2-dioleoyl-sn-glycero-3-phosphatidylcholine (DOPC) neutral nanoliposomes (EPHARNA) to mouse ovarian tumors, which resulted in decreased tumor burden." (PMID 38279277, 2024). "Additionally, they engineered ML and cNK cells to express anti-EphA2 CAR-CD8A-41BB-CD3z and assessed their functional responses against HNSCC cell lines and primary tumor cells." (PMID 39192980, 2024). "This second CAR is responsible for killing cancer cells by recognizing antigens such as EphA2 or IL13Rα2, which are uniformly expressed in cancer cells but not tumor-specific." (PMID 39506843, 2024). "They showed that a lack of EphA2 in the tumour microenvironment, notably in the blood vessel endothelium, hinders tumour angiogenesis and metastases." (PMID 36830852, 2023). "In conclusion, our study provides, for the first time, absolute quantification of RTKs in liver tissue from healthy individuals and cancer patients with a focus on CRLM, reflecting a significant suppression of EGFR, INSR, VGFR3, and AXL, and upregulation of IGF1R, EPHA2 and PGFRB in tumour." (PMID 36890818, 2023). "Finally, Miao and colleagues demonstrated that EphA2–ephrin–A1 interaction strengthened adhesion to collagen I, explaining how the Eph–ephrin system may not only have an important role in the detachment of cancer cells from the primary tumor, but also in the process of bone metastasis formation." (PMID 37895923, 2023). "EphA2 has been shown to be activated through the phosphorylation on serine 897 mediated by AKT, RSK, and PKA kinases and alters downstream signaling, and then facilitating tumor progression." (PMID 36814489, 2023).
tumor (continued). "PLCγ1 promotes tumor cell proliferation in KRAS-mutant LC cells, suggesting that PLCγ1 is a novel interactor of the EphA2 RTK in LC cells and that the EphA2–PLCγ1 signaling axis could be a promising therapeutic strategy for treating LC." (PMID 37370855, 2023). "Of the 11 neoplasm-related genes in these subclusters, the expression of six (ANGPT2, TP73, NOVA1, CDH11, CXCL12, and LAMA1) were significantly repressed in KRT and one (EPHA2) was higher expressed in KRT compared with IMU." (PMID 37654626, 2023). "One of its best-described members, EphA2 has gained increasing attention due to its ligand-dependent (canonical) and ligand-independent (non-canonical) signaling that can either display a tumor suppressive or oncogenic behavior, respectively." (PMID 36998455, 2023). "Collectively, the present results reveal a novel molecular mechanism for non-canonical EphA2 activation under stress conditions in the tumor microenvironment." (PMID 37059179, 2023). "In mouse xenograft and rat syngeneic tumour models, application of 1C1-mcMMAF at 1 mg/kg showed a substantial growth suppression of EphA2-expressing tumours with no detectable negative impacts." (PMID 36830852, 2023). "The EPHA2/ephrinA3axis acts as a responder to low oxygen levels, utilizes SREBP1-mediated ACLY transcription to promote metabolic reprogramming, and induces higher self-renewal and tumor-initiating capacity in HCC cells (EpCam, CD13, and CD24)." (PMID 37444544, 2023). "Due to their implication in cell motility regulation, it is not surprising that both ephrinA5 and EphA2 have been described to influence tumorigenesis and tumor progression." (PMID 37880732, 2023). "In tumours, CSF1R correlated with AXL, EPHA2 with PGFRA, and NTRK2 with PGFRB and AXL." (PMID 36890818, 2023). "The genes with the most frequent SGMs associated with the three mutational processes are clearly enriched in core TSGs, including early oncogenic drivers such as APC, later drivers of tumor progression and metastasis such as CDH1, as well as less-characterized cancer genes such as EPHA2 and MGA." (PMID 37922356, 2023). "The function of EPHA2, LAMC2 and LOXL2 in tumor cells may explain the correlation between the VM score and poor prognosis of LUAD patients." (PMID 37351348, 2023). "One group discovered in breast cancer that increased ECM rigidity could activate the EPHA2/LYN/TWIST signaling pathway that promotes the epithelial-to-mesenchymal transition (EMT), and tumor metastasis." (PMID 35920986, 2022). "With the list now containing a total of 19 relevant preclinical studies, EPHA2 is, undoubtedly, the most studied EPH/ephrin target in BC treatment, the targeting of which mainly results in cell death induction, tumor growth inhibition, as well as anticancer immune system response." (PMID 36499598, 2022). "Importantly, EGFR, MET, EPHA2, MAPK1, MAPK3, and RPS6 kinase pathways were strongly dependent on FLCN in RPTEC and also strongly respond to FLCN reconstitution in this BHD tumor cell line, as highlighted in the UOK257 INKA rankings in orange." (PMID 35863698, 2022). "EphA2-TEA-VV not only killed infected tumor cells but also induced bystander killing of noninfected tumor cells." (PMID 36146629, 2022). "Based on our RNA-seq data analysis, EphA2 and VEGFA were enriched in growth and vasculature development in HCT116 cells; therefore, we evaluated the tumor‐promoting ability of METTL3 and its target genes, EphA2 and VEGFA, by upregulating EphA2 and VEGFA using a GV230 overexpression vector." (PMID 35595748, 2022). "In general, most studies support an oncogenic role for EPHA2 non-canonical signaling and a tumor suppressor role for canonical signaling." (PMID 35673569, 2022). "Therefore, the anti-tumor effects of peptide vaccines targeting MHCI (BIRC5 and EphA2) and MHCII (PADRE) peptides were investigated using a vaccine composed of long multi-epitope peptides in this GL261 mouse model." (PMID 36439089, 2022).
tumor (continued). "The EphA2 RTK is overexpressed in GB while it is expressed at low levels in normal neural tissues, representing an attractive imaging target for delineation of tumor infiltration." (PMID 34209513, 2021). "EphA2 has a clear impact on NSCLC signaling and influences targeted treatment responses including those elicited upon EGFR-TKI treatment or when targeting VEGFR2 expression on tumor cells." (PMID 33671073, 2021). "MM-310, an anti-EphA2 immuno-liposome containing docetaxel prodrug has shown superior tumor penetration and anti-tumor activity in a range of xenograft models compared to free docetaxel and significantly with lower toxicity." (PMID 34926242, 2021). "In the absence of functional EphA2, mutant cells are retained, accelerating premalignant lesion formation and suggesting that EphA2-driven competition is tumor suppressive." (PMID 33891893, 2021). "Multiple studies in tumor cells of different origin have shown that EFNA1 treatment leads to increased tyrosine phosphorylation of EphA2, e.g., at Y588 with a concomitant decrease in phosphorylation of EphA2 at S897." (PMID 33671073, 2021). "Furthermore, consecutive sections of allograft tumor tissues, stained with PAS, CD34, VE-cadherin, or EphA2, were scanned to count the number of MV (CD34+/PAS−) and VM (CD34+/PAS−)." (PMID 34221978, 2021). "Tumor cells showed characteristics of Epithelial-Mesenchymal Transition (EMT) and a high expression of EPHA2 (but not ephrin-A1), using IHC, suggesting a possible link between the receptor and aggressive tumor phenotypes." (PMID 34445116, 2021). "EVs carrying EphA2 improve RAS-ERK oncogenesis and tumor angiogenesis." (PMID 34207163, 2021). "In these tumor-promoting contexts, EphA2 activation relies on the so-called non-canonical EphA2 pathway, which is characterized by phosphorylation at serine 897 by pro-tumorigenic kinases, such as PKA, RSK kinases and Akt." (PMID 34831119, 2021). "Virus-based tumor antigen expression not only induces tumor-infiltrating leukocyte (TIL) and peripheral immune cell phenotypical changes but also produces functional populations with an improved Epha2 antigen response capable of suppressing tumor growth on rechallenge of survivors." (PMID 34599026, 2021). "In our study we confirmed the existence of canonical and non-canonical activation of EphA2 that previously has been reported in different tumor types including NSCLC." (PMID 33671073, 2021). "Last but not least, EphA2 has also been identified as a tumor intrinsic driver of immunosuppression in pancreatic adenocarcinoma, possibly through modulating the levels of the cyclooxygenase-2 COX-2." (PMID 33572284, 2021). "Our results show that in two different C57BL/6 immune-competent tumor models that possess high basal EphA2 expression, OV treatment alone did not elicit an immune-mediated antitumor response." (PMID 34599026, 2021). "Given that EphA2 is overexpressed in GBM specimens, especially in post-therapy GBM stem-like cells, anti-EphA2 CAR T cells may be suited to target GBM at tumor recurrence." (PMID 34298615, 2021). "Thus the phosphorylation of EphA2 at S897 in resistant HCC cells should promote ligand-independent signaling and drive tumor-promoting activity." (PMID 32203105, 2020). "Notably, cisplatin increased EphA2 and pS897/pY588, and BI‐D1870 blocked both the constitutive and cisplatin‐induced EphA2‐pS897 in the HGSC cells with high GPRC5A, concurrently increasing tumor‐suppressive EphA2‐pY588." (PMID 32115889, 2020). "Intrigued by our unexpected observation of platinum‐induced EphA2 upregulation in ex vivo 3D collagen cultures of HGSC patient cells, we used relevant cell models and clinical tumor material to understand the EphA2‐GPRC5A pathway and its clinical implications in OC." (PMID 32115889, 2020).
tumor (continued). "It is imperative that by targeting the EphA3, EphA2, and EphB2 receptors at once, we will be targeting not just the tumor cells, but also key components within the GBM microenvironment that allow GBM to sustain and grow." (PMID 32340173, 2020). "The findings also indicate that miR-1224-5p inhibits cell proliferation, colony formation, migration and invasion in vitro and tumour growth in vivo by targeting TNS4, and subsequently promoting the autophagic degradation of EGFR, and suppressing downstream EFNA1/EPHA2 and VEGFA signalling pathways." (PMID 32732965, 2020). "We found that EPHA2 knockdown did not significantly affect tumor sizes and tumor weights in NOD/SCID mice subcutaneously injected with AGS or MKN45 cells." (PMID 32005975, 2020). "Western blot analysis of tumor tissue lysates showed that ALW reduced the phosphorylation levels of EphA2, STAT3, AKT, and ERK, consistent with the results observed in vitro and the results of stable knockdown of EphA2 observed in vivo." (PMID 32814829, 2020). "The canonical function of EPHA2 is to inhibit cancer proliferation as well as motility whereas the non-canonical pathway EPHA2 promotes tumor survival and metastasis and drives the cells to be more dedifferentiated." (PMID 32679899, 2020). "This discrete pattern was not evident for EphA2 and βDG which showed comparable expression in both glial and mesenchymal tumour elements." (PMID 31463571, 2019). "These regions were smaller and less prominent than in GS tumours, and also showed heterogeneous expression of GFAP, vimentin, EphA2, EphA3 αDG, CD49f and CD31, indicating that this tumour tissue patterning might also occur in GBM (Online Resource 2b)." (PMID 31463571, 2019). "Empty DOPC liposomes, control siRNA in DOPC liposomes, EphA2-targeting siRNA in DOPC liposomes, paclitaxel (100 μg) + control EphA2 siRNA in DOPC liposomes and paclitaxel+EphA2 siRNA in DOPC liposomes were administered after the mice had a tumor size of to 0.5 to 1.0 cm3." (PMID 29861465, 2018). "We showed that leflunomide (LEF) inhibited angiogenesis in a N-butyl-N-(4-hydroxybutyl)-nitrosamine (BBN)-induced bladder carcinogenesis model and a tumor xenograft model, as well as in BCa cell and HUVEC co-culture systems, via significant inhibition of the sEphrin-A1/EphA2 system." (PMID 29367676, 2018). "After 21 days of treatment it was found that EphA2-targeted siRNA inhibited the tumor growth by 43.1% compared to the negative control group." (PMID 29861465, 2018). "We previously reported that extracellular Hsp90 (eHsp90), a known pro-motility and invasive factor, collaborates with EphA2 to regulate tumor invasion in the absence of its cognate ephrin ligand." (PMID 29290990, 2017). "As a target for tumor imaging, a low grade of expression of both EphA2 and EphB4 in normal tissue is essential and has not been thoroughly investigated." (PMID 28165374, 2017). "Given that EPHA2 is one of the key regulators of cell proliferation, migration, invasion and metastatic spread, targeting this RTK in several types of cancers including breast, CRC, lung, brain and prostate impairs tumor growth and metastasis." (PMID 29262644, 2017). "The resulting EphA2-TEA-VV displayed significantly enhanced efficacy by inducing the bystander killing of tumour cells not yet infected with virus." (PMID 29157300, 2017). "To determine whether reduced metastasis was owing to a requirement for EphA2 and RCP in invasive/migratory behaviour of PDAC cells, we isolated a number of cell lines from both control and knockout primary tumours." (PMID 28294115, 2017). "For EphA2, there was no category a, that is, no case where it was clearly expressed on the surface of tumor cells." (PMID 27834817, 2016). "For instance a recent study proposed that EPHB6 could decide the fate of the tumor by interacting with other receptors such as EPHB2 and EPHA2." (PMID 26870995, 2016).